LGALS2 (galectin 2)
Description:
This protein binds beta-galactoside. Its physiological function is not yet known.
Synonyms: HL14
Tractability: Small molecule: it has a binding pocket of medium quality. PROTAC: a small molecule that binds it is known.
Target class: Other cytosolic protein
Gene: Protein-coding gene on chromosome 22 (37,570,248 to 37,582,616, reverse strand). Ensembl gene ENSG00000100079.
Subcellular location (Human Protein Atlas): Mitochondria; Nucleoplasm
Gene Ontology:
Molecular function: protein binding; carbohydrate binding; galactoside binding
Biological process: cell-cell adhesion; positive regulation of apoptotic process; T cell homeostasis; positive regulation of inflammatory response
Cellular component: galectin complex
Genetic constraint (gnomAD): Loss-of-function variants: 7 observed, 11.24 expected, observed/expected ratio (o/e) 0.62, 90% interval 0.35 to 1.17. The upper end of that interval is the gene's LOEUF score, 1.17, which puts it in group 5 of 6, group 1 being the genes least tolerant of losing a copy. Missense variants: 167 observed, 172.3 expected, observed/expected ratio (o/e) 0.97, 90% interval 0.85 to 1.1. Synonymous variants: 86 observed, 67.23 expected, observed/expected ratio (o/e) 1.28, 90% interval 1.07 to 1.53.
Homologues: Orthologues: chimpanzee LGALS2 (98% identical), dog LGALS2 (77% identical), pig LGALS2 (70% identical), rabbit LGALS2 (68% identical), macaque LGALS2 (67% identical), mouse Lgals2 (65% identical), guinea pig LGALS2 (63% identical), rat Lgals2 (63% identical), tropical clawed frog lgals2 (48% identical), zebrafish lgals2b (42% identical), zebrafish lgals2a (36% identical), zebrafish lgals1l1 (34% identical), and 7 more. Paralogues in human: LGALS1 (42% identical), LGALS4 (29% identical), LGALS9 (27% identical), LGALS9B (27% identical), LGALS9C (27% identical), LGALS3 (27% identical), LGALS7 (27% identical), LGALS7B (27% identical), GRIFIN (25% identical), LGALS8 (25% identical), LGALSL (21% identical), CLC (18% identical), and 4 more.
Diseases named in the same sentence as LGALS2 in open-access papers:
LGALS2 is named in the same sentence as 59 diseases in open-access papers, as found by Europe PMC text mining. Sharing a sentence is not in itself a finding about the gene and the disease. The quoted sentences say what the papers report.
breast carcinoma (11 papers, 2016 to 2025). "Up-regulated transcripts and proteins included LGALS2, which has been implicated to restrain tumor progression in colorectal and breast cancer, as well as CRABP2, whose overexpression has been associated with decreased invasiveness of ER+ breast cancer cells." (PMID 40073121, 2025). "The findings from this study need further validation through in vitro and in vivo experiments to confirm the functions of LGALS2 and unravel the underlying molecular mechanisms in breast cancer." (PMID 37838802, 2023). "Our study systematically and comprehensively validates that LGALS2 can be used as a diagnostic/prognostic marker for breast cancer, especially a good diagnostic marker for TNBC, and that it participates in tumor immunotherapy by regulating T cells." (PMID 37838802, 2023). "LGALS2 overexpression has been linked to a better prognosis in breast cancer." (PMID 37693315, 2023). "In summary, our study shows that LGALS2 could be used as a diagnostic and prognostic marker for breast cancer, and that it regulates the biological activity of T cells to participate in tumor immunotherapy and reduces the occurrence of clinical drug resistance in patients." (PMID 37838802, 2023). "Furthermore, we show that LGALS2 could be used as a diagnostic marker for breast cancer (AUC = 0.601), and has a better diagnostic value in TNBC (P < 0.0001)." (PMID 37838802, 2023). "Thus, upregulating LGALS2 expression was associated with the activation and differentiation of T cells, induction of immune responses and promotion of the necrosis or apoptosis of breast cancer cells." (PMID 37838802, 2023). "The levels of galectin-2, -4, and -8 in blood were significantly elevated in patients with colon and breast cancers, particularly in those with metastases." (PMID 39857769, 2025). "In this study, we found that LGALS2 expression was low in breast cancer patients and was lower in the breast tissue relative to other tissues, and patients with high LGALS2 expression had a better prognosis (P = 0.014)." (PMID 37838802, 2023). "In recent years, the role of LGALS2 in cancer development has been explored and it has been proposed as a potential prognostic biomarker for breast cancer and colorectal cancers." (PMID 36389761, 2022). "Similarly, LGALS2 has been identified as a key marker within TLS in breast cancer, demonstrating a positive correlation with prolonged survival." (PMID 39620224, 2024). "The role of LGALS2 expression in breast cancer drug resistance was therefore studied." (PMID 37838802, 2023). "As a novel molecular biomarker for breast cancer treatment, LGALS2 may enable the development of novel immunotherapy strategies that are of a high clinical relevance in the future." (PMID 37838802, 2023). "In addition, the expression levels of LGALS2 in different tissues (n = 29) and different human breast cancer cell lines (n = 68) were also analyzed based on the CCLE database, which was found to be consistent with the TCGA database results." (PMID 37838802, 2023). "Interestingly, levels of galectin-2 in the blood circulation have been shown to be significantly higher in both colon and breast cancer patients in comparison to healthy people." (PMID 36613785, 2022). "Therefore, reducing the methylation level of the LGALS2 promoter, thereby reversing the occurrence and development of breast cancer, could serve as a new strategy for breast cancer treatment." (PMID 37838802, 2023). "Therefore, LGALS2 could also serve as a potential marker for breast cancer immunotherapy." (PMID 37838802, 2023). "High level of galectin-2 mRNA was shown to correlate with a favourable prognosis and overall survival in HER-2 overexpressing breast cancer and in luminal B-type breast cancer patients." (PMID 36613785, 2022). "Whether the low expression of LGALS2 in breast cancer patients was related to DNA methylation modification has not yet been reported." (PMID 37838802, 2023).
breast carcinoma (continued). "Therefore, we speculated that LGALS2 might not be directly involved in the migration and development of breast cancer." (PMID 37838802, 2023).
colitis (8 papers, 2016 to 2023). Inflammation of the colon. "Previous studies reported that LGALS2 induced T lymphocyte apoptosis, improved colitis, and prevented preeclampsia." (PMID 37838802, 2023). "The role of galectin-2 in T cell apoptosis was studied in mice in which galectin-2 levels were inversely correlated to the occurrence of colitis." (PMID 36873388, 2023). "Mouse treatment with recombinant galectin-2 strongly reduced the rate of colitis by inducing T-cell apoptosis, located in the mucous membranes." (PMID 36873388, 2023). "In an animal study, galectin-2 expression was observed to be substantially lower in the colonic lamina propria of DSS-treated colitis mice in comparison to untreated control mice." (PMID 36613785, 2022). "Administration of exogenous galectin-2 at the onset of DSS-induced colitis preserved the integrity of colonic crypts and epithelial architecture that would otherwise be caused by DSS damage." (PMID 36613785, 2022). "Based on these findings, further investigations into the therapeutic potential of galectin-2 were conducted; these showed a significant reduction of inflammation in acute and chronic mice colitis-models." (PMID 32244351, 2020). "Added galectin-2 can support epithelial wound healing and suppress lamina propria T-cells to ameliorate experimental colitis in mice." (PMID 26885508, 2016). "In addition, they demonstrated that galectin-2 induces apoptosis and ameliorates acute and chronic colitis in mice." (PMID 33134350, 2020). "To examine the role of Gal2 in colitis, we employed the dextran sodium sulfate (DSS)-induced acute colitis model in mice with (WT) or without Lgals2 (Gal2-KO) and showed that Gal2 deficiency ameliorated DSS-induced colitis." (PMID 33110234, 2021).
coronary artery disease (8 papers, 2015 to 2023). "Higher galectin-2 levels in monocytes and macrophages are linked to low arteriogenic response in coronary artery disease patients and inflammation." (PMID 27903268, 2016). "Galectin-2 expression in monocytes is associated with a low natural arteriogenic response in patients suffering from ischemic heart disease." (PMID 25884209, 2015). "How galectin-2 polymorphism is involved in coronary heart disease development is however unknown." (PMID 36613785, 2022). "Galectin-2 gene polymorphism, together with CXCL16, AGTR1 and PPARG gene polymorphism, was shown to be closely associated with the development of coronary heart diseases in patients." (PMID 36613785, 2022). "Alteration of galectin-2 expression occurs in inflammatory bowel disease, coronary artery diseases, rheumatoid arthritis, cancer, and pregnancy disorders and has been shown to be involved in disease pathogenesis." (PMID 36613785, 2022). "Administration of anti-galectin-2 antibody also inhibited the progression of atherosclerosis and favoured the generation of new arteries in ischemic heart disease in a mouse model." (PMID 36613785, 2022). "Recently, results of our group showed involvement of Galectin-2 in arteriogenesis in patients with ischemic heart disease." (PMID 25884209, 2015). "We demonstrated that galectin-2 mRNA expression is increased in both monocytes and macrophages of coronary artery disease (CAD) patients with a low arteriogenic response and that galectin-2 impairs arteriogenesis in vivo in a murine model." (PMID 25884209, 2015). "The regulation of galectin-2 may establish a new therapeutic strategy for the stimulation of arteriogenesis in patients with coronary artery disease." (PMID 33134350, 2020). "Targeting of galectin-2-mediated responses in monocytes and macrophages may provide new therapeutic strategies in coronary artery disease patients with a low arteriogenic response and a high expression of galectin-2." (PMID 25884209, 2015). "studies so far suggest that galectin-2 expression and secretion may contribute to enhancing the mucosal barrier of the gastrointestinal tract and be involved in regulation of the pathogenesis of coronary artery diseases, rheumatoid arthritis, cancer, and pregnancy disorders." (PMID 36613785, 2022).
myocardial infarction (7 papers, 2018 to 2025). Gross necrosis of the myocardium, as a result of interruption of the blood supply to the area, as in coronary thrombosis. "Studies on the Japanese population showed the existence of a functional single-nucleotide polymorphism (SNP) rs7291467 (C3279C-T) in the galectin-2 coding gene that was strongly associated with myocardial infarction." (PMID 36873388, 2023). "C3279C-T genetic substitution affected the transcriptional levels of galectin-2 in vitro, altering the secretion of lymphotoxin-α and inflammation, indicating on the link between galectin-2 function and pathogenesis of myocardial infarction." (PMID 36873388, 2023). "Lymphotoxin-α and β-tubulin have also been reported to interact with galectin-2 in macrophages and in atherosclerotic plaque of the heart muscle following myocardial infarction." (PMID 36613785, 2022). "The presence of galectin-2 shows to favour the conversion of activated T cells to T helper cells in myocardial infarction." (PMID 36613785, 2022). "A functional SNP in LGALS2 encoding galectin-2, which resulted in altered LTA secretion, was likewise linked to an increased risk of myocardial infarction, according to the study." (PMID 36499335, 2022). "The involvement of galectin-2 in cardiovascular events was first implicated from the identification of galectin-2 as a binding partner of lymphotoxin-α, a cytokine that is involved in the pathogenesis of myocardial infarction (MI), in COS7 non-steroidogenic and U937 pro-monocytic cells." (PMID 36613785, 2022).
gastric cancer (6 papers, 2020 to 2025). A primary or metastatic malignant neoplasm involving the stomach. "In this case, Jung and colleagues reported that loss of galectin-2 in gastric cancer cells was associated with the aggressiveness of cancer cells, revealing a commonality between galectin-2 and other galectins in playing contradictory roles in tumor progression, depending on the type." (PMID 37753083, 2023). "This indicates that high galectin-2 expression within the tumour may be associated with a favourable outcome for gastric cancer patients." (PMID 36613785, 2022). "A reduced level of galectin-2 was observed in lesion of Helicobacter-induced gastric cancer in mice in comparison to normal mice." (PMID 36613785, 2022). "Galectin-2 has also been found in the cytosol and nuclei of gastric cancer cells." (PMID 37753083, 2023). "Elevated expression of LGALS2 reportedly inhibits the development of CRC and lymph node metastasis of gastric cancer." (PMID 35968507, 2022). "A 12 fold higher level of galectin-2 was observed in lymph node metastasis-negative gastric cancer tissue than in advanced and lymph node metastasis-positive gastric cancer tissue." (PMID 36613785, 2022).
gestational diabetes (4 papers, 2020 to 2023). Carbohydrate intolerance first diagnosed during pregnancy. "Overexpression of galectin-2 was observed in foetal STB and maternal decidua of gestational diabetes mellitus (GDM) placenta." (PMID 36613785, 2022).
intrauterine growth restriction (4 papers, 2016 to 2022). "Sexually dimorphic expression of galectin-2, -13/LGALS13 and -14/LGALS14 in human placenta was shown under physiological conditions and in intrauterine growth restriction (IUGR), most likely reflecting genetic and hormonal differences between sexes." (PMID 35008499, 2021). "Interestingly, reduction of galectin-2 expression was observed in the placenta of all compartments of male, but not female, intrauterine growth restriction (IUGR) cases in the third trimester of pregnancy." (PMID 36613785, 2022). "Interestingly, in cases of intrauterine growth restriction (IUGR), there was no change in expression in female placentas compared to controls; however, expression of Lgals2 in male IUGR placentas was reported to be decreased compared to controls." (PMID 31231368, 2019).
colon tumor (3 papers, 2021 to 2023). "LGALS2 encodes the glycan-binding protein Galectin 2 (Gal2), which is predominantly expressed in the gastrointestinal tract and downregulated in human colon tumors." (PMID 33110234, 2021). "LGALS2 is an oxidative stress-responsive gene that inhibits colon tumor growth." (PMID 36591255, 2022).
Hypertension (3 papers, 2017 to 2022). The presence of chronic increased pressure in the systemic arterial system. "Furthermore, a C3279T polymorphism in LGALS2 gene (encoding Gal-2), has been associated with diastolic blood pressure in RA patients at increased risk for hypertension." (PMID 30687310, 2018).
inflammatory bowel disease (3 papers, 2022 to 2024). A spectrum of small and large bowel inflammatory diseases of unknown etiology. "Altered expression of galectin-2 has been implicated in the pathogenesis of inflammatory bowel disease (IBD), pregnancy-related disorders, and several cancers." (PMID 39365081, 2024). "Altered expression of galectin-2 is observed in inflammatory bowel disease, several pregnancy-related disorders and various cancers and has been shown to be involved in their disease pathogeneses." (PMID 36613785, 2022). "Subsequently, since LGALS2 is abundantly expressed in the intestinal epithelium and has been shown to induce apoptosis of T cells, many studies have focused on the functional role of LGALS2 in inflammatory bowel disease." (PMID 36389761, 2022).
antiphospholipid syndrome (2 papers, 2022 to 2024). A disorder caused by the presence of autoantibodies directed against phospholipids, causing a hypercoaguable state, which may result in blood clots, stroke, heart attack, and in women, significant pregnancy-related complications, including miscarriage and still birth. "Antiphospholipid syndrome is prevalent in individuals with PE and they have lower levels of galectin-2 (gal-2)." (PMID 38731197, 2024).
Insulin resistance (2 papers, 2018 to 2020). Increased resistance towards insulin, that is, diminished effectiveness of insulin in reducing blood glucose levels. "The increased galectin-2 expression in GDM characterized in this study might contribute to the proinflammatory milieu of insulin resistance via macrophage dysregulation." (PMID 32244351, 2020).
Miscarriage (2 papers, 2021 to 2023). A pregnancy that ends at a stage in which the fetus is incapable of surviving on its own, defined as the spontaneous loss of a fetus before the 22th week of pregnancy. "Previous studies pointed out a decreased level of galectin-2 in the placental tissue of miscarriages, preeclampsia, and male cases of intrauterine growth restriction (IUGR)." (PMID 37998731, 2023). "As galectin-2 might play a role in angiogenesis, lack of galectin-2 in the placenta may contribute to miscarriages." (PMID 37998731, 2023).
Obesity (2 papers, 2018 to 2021). Accumulation of substantial excess body fat. "The closely related gene Lgals3 has already been shown to protect from HFD-induced obesity in mice, but functional evidence for Lgals2 in context with T2D development is still missing." (PMID 33880624, 2021).
pregnancy diseases (2 papers, 2022). "As apoptosis of regulatory T cells is a major contributor to immunity-related pregnancy disorders, galectin-2-mediated reduction of T cell apoptosis may help to prevent immunity related pregnancy disorders." (PMID 36613785, 2022).
triple-negative breast carcinoma (2 papers, 2016 to 2022). An invasive breast carcinoma which is negative for expression of estrogen receptor (ER), progesterone receptor (PR), and human epidermal growth factor receptor 2 (HER2). "A multidimensional CRISPR screening study in mice on the other hand suggested that the galectin-2 gene is a positive regulator of immune escape in triple-negative breast cancer." (PMID 36613785, 2022). "Tumours inoculated with galectin-2 transfected triple-negative breast cancer 4T1 cells in BALB/c mice showed to grow significantly faster and bigger than inoculated with control vector transfected 4T1 cells and administration of an anti-galectin-2 antibody reduced the tumour growth." (PMID 36613785, 2022).
acute myeloid leukemia (1 paper, 2023). Acute myeloid leukemia (AML) is a group of neoplasms arising from precursor cells committed to the myeloid cell-line differentiation. "KEGG showed that the LGALS2 had high expression in the allograft rejection signaling pathway, acute myeloid leukemia, and intestinal immune network for IgA production." (PMID 37528394, 2023).
amebic colitis (1 paper, 2024). "For example, exogenous galectin-2 has been found to be associated with gastrointestinal wound healing and integrity of the epithelial architecture in IBD, while amebic colitis and IBD not only have similar clinical manifestations but also occur as relatively frequent co-infections (44, 54, –, 58)." (PMID 39365081, 2024).
asthma (1 paper, 2025). "Galectin 2 (Gal-2) could exert a protective role during allergic inflammation by inducing apoptosis of CD8+ T cells, while Gal-3 seems to exacerbate asthma, atopic dermatitis, and EAE by promoting an (Immunoglobulin E) IgE increase." (PMID 40650248, 2025).
coronary atherosclerosis (1 paper, 2023). Atherosclerosis of the coronary vasculature. "Moreover, a polymorphism in the LGALS2 gene has been related to the severity of coronary atherosclerosis, but contrary to BRAP, not with MI." (PMID 37892153, 2023).